AFP (alpha fetoprotein)
Diseases named in the same sentence as AFP in open-access papers (continued):
Sharing a sentence is not in itself a finding about the gene and the disease.
cancer (continued). "Network analysis of upregulated genes revealed their enrichment in signatures of cancer cell growth and fetal liver (e.g., AFP, DLK, EPCAM and KRT19)." (PMID 37173882, 2023). "The development of AFP detection technology with high sensitivity is necessary for the early detection of some cancers and the clinical detection of AFP." (PMID 36979562, 2023). "The higher the preoperative serum AFP level, the greater the probability of cancer cells metastasizing through the bloodstream." (PMID 37519810, 2023). "For example, in our previous studies we combine the analytical merits of AuNPs and CNPs in the fabrication of an immunosensor for the detection of a cancer biomarker known as Alpha-fetoprotein (AFP)." (PMID 36831958, 2023). "As the most commonly used marker for evaluating HCC, serum AFP showed an AUC of 0.927 (95% CI: 0.886–0.969) and 0.981 (95% CI: 0.966–0.997) to distinguish patients with cancer from CHB and normal individuals." (PMID 37735632, 2023). "Above all, we have found the unique ECL properties of GSH-Au2.5Pt NCs which have been applied in the fast, sensitive, and accurate detections of AFP cancer biomarkers as signal tags." (PMID 37232911, 2023). "Many of these hits are serum proteins described to have aberrant N-glycosylation during cancer progression, such as AFP and the protein disulfide isomerase PDIA3." (PMID 36961502, 2023). "The pathological subtype, T stage, M stage, surgery, AFP, and cancer history were confirmed as the independent prognostic factors for cancer-specific survival in the multivariable analyses, and then a nomogram was developed based on these variables." (PMID 35463333, 2022). "AFP is wildly applied in clinical treatments, including monitoring specific types of cancer and screening for fetal malformation." (PMID 35712096, 2022). "Aptamer: In 2012, a first report demonstrated that an RNA aptamer was able to detect cancer cells and inhibit proliferation in an alpha-fetoprotein (AFP) expressing HCC cell-line via the suppression of oncogene expression in c-jun and c-fos." (PMID 35600358, 2022). "Using the combination of ctDNA and AFP as detective indicators distinguished HCC patients from non-cancer control participants with a SEN of 0.82 (95% CI [0.77–0.86], I2 statistic: 85.81%) and a SPE of 0.84 (95% CI [0.76–0.90], I2 statistic:93.32%)." (PMID 36348665, 2022). "Our findings provide insights into the common functions of evolutionary conserved SLiMs and putative involvement of AFP in response to external and internal stimuli during cellular adaptation during embryonic development and cancer." (PMID 36670957, 2022). "The pathological subtype, T stage, M stage, surgery, alpha-fetoprotein, and cancer history were confirmed as the independent predictors in patients with rare subtypes." (PMID 35463333, 2022). "Alpha fetoprotein fragments not only deliver drugs that selectively destroy cancer cells which highly express AFP receptors (AFPRs), but also inhibit the role of AFP in promoting malignant behaviours of cancer cells." (PMID 36181321, 2022). "High plasma levels of alpha-fetoprotein (AFP) levels in HCC patients are believed to be due to the EMT associated with TGF-β, as well as the cancer stem cells triggered through TGF-β signaling." (PMID 36080304, 2022). "Here, we used a local sequence alignment algorithm for a computational search of SLiMs that have sequence similarity to two biologically active peptide segments of human alpha-fetoprotein (AFP), a major mammalian embryo-specific and cancer-related protein." (PMID 35629968, 2022). "Our research of β-catenin pathways in HBL patients revealed that the β-catenin-TCF4-CEGRs/ALCDs pathway accelerates the proliferation of cancer cells and increases the expression of many oncogenes, including AFP and GPC3." (PMID 36551548, 2022).
cancer (continued). "The pathological subtype, T stage, M stage, surgery, AFP, and cancer history were confirmed as the independent prognostic factors for cancer-specific survival in patients with rare HCC subtypes." (PMID 35463333, 2022). "Despite the fact that plasma protein biomarkers are commonly used in clinical management for different cancers, such as AFP, CEA, PSA, and CA15-3, some cancer patients are not positive for these biomarkers." (PMID 35938032, 2022). "Our data suggest that AFP can use the SLiMs of interest to provide cellular adaptation to stress conditions during embryonic development and cancer growth." (PMID 36670957, 2022). "Alpha-fetoprotein is a traditional cancer biomarker that is used to monitor HCC treatment and recurrence; however, 35–45% of HCC patients have low serum AFP levels (<20 μg/L)." (PMID 35141283, 2022). "AFP not only can play an important role in regulating the proliferation of tumors, but also can enhance the anti-apoptotic effect of cancer cells." (PMID 33718192, 2021). "Alpha-fetoprotein (AFP) is a commonly used cancer marker for early screening, diagnosis and treatment evaluation." (PMID 34147096, 2021). "In human medicine, protein biomarkers such as RECAF and AFP have demonstrated limited sensitivity and specificity for cancer detection." (PMID 33834049, 2021). "Because HCC and other cancer cells regain the ability to take up AFP via its receptor and exert malignant behaviors, AFP delivery of cytotoxins is used to target and kill cancer cells." (PMID 33898423, 2021). "Overexpression of HSPA4 considerably correlated with cancer stage and alpha-fetoprotein (AFP) level in HCC." (PMID 34754620, 2021). "For cancer-specific survival, 32 points for her marital status, 0 points for her age, 60 points for her race, 0 points for differentiation, T stage, size, and AFP." (PMID 34187430, 2021). "A combined diagnostic approach consisting of ultrasound imaging, magnetic resonance imaging, computed tomography, and detecting alpha-fetoprotein (AFP) levels in patient sera is used to diagnose cancer and predict HCC prognosis." (PMID 34680327, 2021). "In AdCN103, the 24 bp deletion of E1A is combined with a modified hTERT promoter and in SynOV1.1 (Ad5-Delta-24-RGD-hGMCSF) with an enhanced cancer-specific alpha-fetoprotein (AFP) promoter." (PMID 34638863, 2021). "At present, most studies have found that cytoplasmic AFP can promote the occurrence of HCC by promoting the proliferation of cancer cells, inhibiting apoptosis and inducing immuno-suppression." (PMID 34680245, 2021). "AFP and cancer cells followed the same kinetics, whereas PIVKA-II time/dose dependent fluctuations were influenced also by tissue ischemia." (PMID 33922938, 2021). "Secreted AFP has many functions, such as immunosuppression, and it regulates the malignant behaviors of cancer cells through mediation by AFPR." (PMID 33898423, 2021). "Alpha-fetoprotein (AFP) is a multifunctional glycoprotein of ca. 70 kDa with a dual regulatory role in cancer and fetal activity." (PMID 33499136, 2021). "Here, we also categorize recombinant AFP (rhAFP) as an unique AIF because it can be used as a vector to deliver drugs to kill cancer cells." (PMID 33898423, 2021). "We excluded the presence of other cell types including cancer cells, immune cells, and endothelial cells by staining with the corresponding markers α-fetoprotein (AFP), epithelial cell adhesion molecule (EpCAM), cluster of differentiation 45 (CD45), and CD31." (PMID 32932015, 2021). "Such a kind of gold microarray wells-embedded gradient microfluidic channel design can offer a convenient and reproducible SERS-based quantitative immunoassay platform for cancer biomarkers such as alpha-fetoprotein (AFP) model protein marker AFP antigen." (PMID 34357236, 2021). "Multivariate Cox regression analysis revealed that RORA was an independent prognostic factor in the TCGA-LIHC dataset after controlling for AFP, cancer size, and TNM stage." (PMID 33842355, 2021).
cancer (continued). "Hyperbranched DNA-LaMnO3 perovskite (DNA-LMO) nanobiocomposites loaded with three different metal ions were used as redox probes for simultaneous discrimination of three different biomarkers of cancer, AFP, CEA, and PSA." (PMID 33499136, 2021). "Alpha-fetoprotein (AFP) entrance into cancer cells is mediated by AFP receptors (AFPRs) and exerts malignant effects." (PMID 33718192, 2021). "The receptors take up AFP and provide nutrients to cancer cells and bone marrow mesenchymal stem cells through shuttling; thus, AFP delivery of drugs instead of nutrients kills MDSCs and cancer cells." (PMID 33898423, 2021). "In some cancers, full-length glycosylated AFP has immunosuppressive effects by stimulating cancer growth and directly activating MDSCs (Pak, 2018a,b)." (PMID 33898423, 2021). "The effectiveness of sorafenib in reducing cancer cells replication was defined by the model parameter εr = 1/[1 + ψ1 × F(t)del], the value of ψ1 = 10 was obtained by AFP fitting and yielded a 13.5% decline once reached the steady state of drug activity." (PMID 33922938, 2021). "Fragment AIFs include AFP-3BC, rAFP3D, and r3dAFP, which are fragments of protein derived from AFP domain-3, and they can deliver drugs and be endocytosed by cancer cells with high AFPR expression." (PMID 33898423, 2021). "Many lines of evidence have indicated that AFP inhibits the immune response in patients with cancers." (PMID 33898423, 2021). "Before the 21st century, researchers put more emphasis on serum levels of AFP and their effect on the proliferation, migration, apoptosis and immune escape of normal and cancer cells." (PMID 34680245, 2021). "Transformed cancer cells including hepatocytes can regain this ability to synthesize AFP and have therefore been used as blood-based biomarkers for HCC diagnosis." (PMID 34680327, 2021). "Among others, a cyclo [EMTOVNOGQ] peptide from alpha-fetoprotein (AFP), a human protein produced during pregnancy, was tested for activity against cancer cells." (PMID 34796903, 2021). "When the serum concentration of AFP is greater than 50 ng/ml in adult blood, it stimulates tissue regeneration or hematopoiesis, and it is also used by cancer cells to provide nutrients and stimulate growth." (PMID 33898423, 2021). "One of the representative fucosylation-related cancer biomarkers is fucosylated alpha-fetoprotein (AFP), which is named the AFP-L3 fraction." (PMID 34948129, 2021). "Elevated levels of cancer biomarkers, such as α-fetoprotein (AFP), in human serum indicates early stage development of various cancer types such as epithelial ovarian tumors, nasopharyngeal cancer, and hepatic carcinoma." (PMID 34684966, 2021). "Model analysis pointed out some differences between the two biomarkers: the mean life-time of PIVKA-II (2.0–5.0 days) was shorter than that of AFP (9.1–10.0 days in all cases but one), the latter being closer to that of cancer cells (9.1 days)." (PMID 33922938, 2021). "AFP and PROM1 are accepted markers for cancer stem cells in the liver and are associated with recurrence, metastasis and chemoresistance in HCC." (PMID 34830835, 2021). "The aptasensor detected AFP in cancer patients’ serum samples with low interference from BSA, IgG, and other cancer-related proteins." (PMID 33499136, 2021). "Using an immunohistochemical marker for AFP, cancer cells were shown to express AFP, specifically in their nuclei." (PMID 33607799, 2021). "A recent meta-analysis evaluated the effectiveness of screening with ultrasound versus using ultrasound and AFP in detecting early cancer." (PMID 34372524, 2021). "Early studies in the 1980s demonstrated that AFP was capable of inhibiting cancer cell growth and differentiation." (PMID 33009373, 2020). "Serum biomarkers such as AFP offer an alternative avenue for real-time monitoring of cancer burden but with clear disadvantages in the clinical setting." (PMID 32071283, 2020).
cancer (continued). "To identify driver oncogenes associated with high AFP concentration in HCC, we performed transcriptomic microarray analysis in paired cancer samples." (PMID 32350243, 2020). "It is also noteworthy that FBXL19-AS1 has been reported to be associated with a variety of cancers, and therefore, the need to combine FBXL19-AS1 and AFP to enhance the diagnostic specificity of HCC should be emphasized." (PMID 33344260, 2020). "When this biomarker were applied together with serum AFP, the sensitivity of the combined test was approximately 85% for early cancer and reached 100% for detecting intermediate and advanced stage HCC." (PMID 32330203, 2020). "Microfluidic chip electrophoresis (MCE) detection of three cancer biomarkers AFP, CEA, and carbohydrate antigen 199 (CA199) was reported using endonuclease‐linked multiplex immunoassay." (PMID 32670744, 2020). "Heterogeneity in meta-analysis approaches to HCC management with ultrasonography and AFP in patients of 14 countries with different and distinct outcomes justifies early cancer detection requirements." (PMID 33585001, 2020). "The small size of nanobodies can facilitate the early diagnosis and prevention of cancer by detecting or defining cancer biomarkers, such as AFP, CAIX, PMSA, TAG-72, or HER2." (PMID 32090077, 2020). "AFP is a cancer-related antigen frequently expressed in HCC and used as a marker for HCC diagnosis and therapeutic efficacy." (PMID 32132566, 2020). "AFP is a cancer-related antigen unique to HCC and has been reported to be a possible therapeutic target for immunotherapy." (PMID 32132566, 2020). "As such, the expression of AFP in healthy individuals is believed to be rare; therefore, the antigen is considered a promising target for cancer immunotherapy." (PMID 32132566, 2020). "We correlated TAP levels with a wide variety of clinical indicators as well as established cancer markers, including alpha fetoprotein (AFP) and carbohydrate antigen 19-9 (CA19-9)." (PMID 32176062, 2020). "Univariate analyses showed that the HRs of overall and cancer-specific survival relative to the AFP+US group were 0.65 and 0.59 for the AFP group, and 0.54 and 0.46 for the US group, respectively (all Ps≤0.001)." (PMID 32845895, 2020). "Although efforts have been made to determine the role of AFP in cancer, the findings from different time periods are contradictory." (PMID 33009373, 2020). "The differences in cell differentiation and cancer-related genes (AFP, NOTCH1, CSF1, NOTUM, TGFβ, and vimentin genes) implied different biological characteristics between cells cultured in the 3D and 2D models." (PMID 32582546, 2020). "AFP can promote cancer cell proliferation through binding AFP receptor (AFPR), activating PI3K/AKT and many other cancer related genes 34-38." (PMID 31897235, 2020). "For example, graphitic carbon nitride (g-C3N4) was used in the development of a split protocol for the photoelectrochemical (PEC) immunoassay of alpha-fetoprotein (AFP)-a cancer biomarker." (PMID 33050361, 2020). "The AFP group had significantly better overall and cancer-specific survival than the AFP+US group after adjusting for covariates (adjusted hazard ratios [HRs] 0.68 and 0.62, respectively)." (PMID 32845895, 2020). "We performed correlation analyses of blood metabolites of HCC patients against cancer stage, sex, number of focal lesions, size of focal lesion, AFP levels and current HBV and HCV infections." (PMID 33396945, 2020). "Additionally, we tested anti-ATIC-autoantibody biomarker and conventional biomarker AFP simultaneously in the patient’s sera and suggested that the combinational measurement of two biomarkers generated by different mechanisms can enhance the diagnostic accuracy in cancer." (PMID 33352757, 2020).
cancer (continued). "In solid cancers, the clinical use of CSC specific biomarkers is very limited, besides the use of the carcinoembryonic antigen (CAE), fragments of the cytokeratin 19 (YFRA 21-1) and the alpha-fetoprotein (AFP) that is expressed by cancer stem cells." (PMID 32849491, 2020). "We included, from a hospital-based cancer registry, 1,776 asymptomatic adults who were surveilled biannually with the AFP test and US and eventually diagnosed with HCC between 2007 and 2015." (PMID 32845895, 2020). "In this study, we present the implementation of a sensitive fluorescent immunosensor for the detection of AFP, which is used as a common cancer-related model protein." (PMID 31921529, 2019). "With regard to cancer vaccination, intradermal injection of AFP peptide or adenoviral vector was used for HCC (NCT00093548)." (PMID 31769427, 2019). "We herein report a case of AFP-producing carcinoma of the EGJ in which long-term survival was achieved through multidisciplinary therapy." (PMID 29457212, 2019). "AFP-producing carcinoma is thought to have a high potential for metastasis, particularly liver metastasis and thus show a poor prognosis." (PMID 29457212, 2019). "We reported a rare case of an AFP-producing carcinoma of the esophagogastric junction, in which long-term survival was achieved through multidisciplinary therapy that included surgery, chemotherapy, and PEIT." (PMID 29457212, 2019). "The further accumulation of similar cases will be useful for establishing an appropriate therapeutic strategy for AFP-producing carcinomas that develop at the EGJ." (PMID 29457212, 2019). "AFP-producing carcinoma of the gastrointestinal tract is considered to have a high potential for liver metastasis." (PMID 29457212, 2019). "The most validated traditional cancer markers include alpha-fetoprotein (AFP), carcinoembryonic antigen (CEA), and carbohydrate antigen (CA)." (PMID 29713393, 2018). "Most of the currently used clinical cancer biomarkers, including alpha-fetoprotein (AFP), are tissue-secreted antigens that can be detected by immunological methods." (PMID 29954402, 2018). "Laboratory investigations revealed raised lactate dehydrogenase with normal serum β-human chorionic gonadotropin, alpha-fetoprotein, and cancer antigen-125 levels." (PMID 30424819, 2018). "We have shown that 5 cancer biomarkers including PSA, AFP, CEA, CA125, and CA19-9 encoded by NTP, BTP, TFTP, DFTP, and DCTP can be quantitatively detected in a single spectral reading." (PMID 29717124, 2018). "Human AFP-producing cancers predominantly arise in the stomach and display poorly differentiated histology and show dismal prognosis." (PMID 29802314, 2018). "Although AFP is expected to play a certain role in antitumor immunity, it is still useless to stimulate the immune cells and produce substantial effects on cancer cells due to its weak immunogenicity." (PMID 29805966, 2018). "Serum levels of cancer markers (AFP and GGT), TGFβ1, and liver enzymes (ALT, AST, and ALP) were significantly higher in the CSC-Ex group, followed by the PBS group as compared to the normal group." (PMID 30224923, 2018). "The patient received adjuvant chemotherapy with capecitabine and oxaliplatin (CAPOX) for 3 months in consideration of high recurrence rate in AFP-producing cancer." (PMID 30191347, 2018). "Treatment for AFP-producing cancer is often performed according to conventional methods, but oncological outcomes of both surgery and chemotherapy are poor." (PMID 30191347, 2018). "HCC cell lines also show dissimilar expression levels of many known cancer-associated proteins such as caveolin-1 (CAV1), alpha fetoprotein (AFP), and WNT signaling molecules." (PMID 30176945, 2018). "This assay proved that the quantification of deglycosylated AFP has much better sensitivity and specificity toward differentiating HCC cancer samples from controls when compared to measurements of total AFP." (PMID 28265552, 2017).